CEMIP (cell migration inducing hyaluronidase 1)
Diseases named in the same sentence as CEMIP in open-access papers (continued):
Sharing a sentence is not in itself a finding about the gene and the disease.
tumor (continued). "Importantly, this effect could be reproduced with CEMIP knockout tumor cells if mice were preinjected with only CEMIP wild-type EVs." (PMID 39851567, 2025). "In addition, we demonstrated that CEMIP-mediated ECM stiffening could promote tumor progression in a stiffness-dependent manner." (PMID 36639658, 2023). "Besides, we demonstrated that CEMIP could enhance the extent of tumor metastasis and angiogenic potential." (PMID 36639658, 2023). "Therefore, CEMIP has emerged as a potential therapeutic target to suppress tumor malignancy." (PMID 37668818, 2023). "Thus, CEMIP could be a novel and potential focus for tumor diagnosis and treatment, but further studies on the regulatory role of CEMIP in vivo and in vitro are still needed." (PMID 36451490, 2022). "In addition to these rather general observations, CEMIP has also been ascribed specific functions, many of which could potentially contribute to its tumor- and metastasis-promoting functions." (PMID 36291875, 2022). "To investigate the cause of decreased tumor growth in CEMIP negative cells in vivo, we examined CEMIP expressing and CEMIP negative tumors by immunostaining for markers of apoptosis (cleaved caspase-3), proliferation (Ki-67), leukocyte infiltration (CD45), and vascularization (CD31)." (PMID 26437221, 2015). "However, tumor cells at the invasive front and in the submucosa were positively stained for CEMIP." (PMID 26009875, 2015). "The simultaneous increase in CEMIP expression facilitates the production of LMWHA, and increased LMWHA levels promote tumor proliferation." (PMID 39858106, 2025). "Other studies have highlighted the interaction between cell migration inducing hyaluronidase 1 (CEMIP), a cell migration inducer protein, and GRP78, which helps tumor cells adapt to hypoxia." (PMID 40278350, 2025). "Decreases in HAS3 and CEMIP expression were also confirmed, suggesting a reduction in LMWHA production by tumor cells." (PMID 39858106, 2025). "In summation, the molecules ZNF165, MXRA7, CEMIP, ARL4C, and CERCAM collectively represent prospective therapeutic nexus points in impeding tumor advancement." (PMID 39624211, 2024). "Notably, tumor cells could release exosomal CEMIP to promote metastasis." (PMID 36639658, 2023). "Most of the TMEM119+ FIBs appeared to be positioned peripherally and juxtaposed to KRT14+ tumor nests, to a greater extent than those observed for CLIC2+ and CEMIP+ FIBs or sparse ASPN+ FIBs." (PMID 35687691, 2022). "Our finding that REST associated sequence elements overlap with the CpG island within the CEMIP locus will have important implications on the epigenetic regulation of this gene by REST and in tumor metastasis." (PMID 35177031, 2022). "In the group with high expression of CEMIP, the pathways and hallmarks significantly enriched were related to antigen presentation and EMT, which again revealed the entanglement of CEMIP with the EMT pathway and tumor immune infiltration." (PMID 34966410, 2021). "One possible explanation would be that CEMIP exerts its pro-survival effects through EMT, a process that promotes tumor progression, as it’s been shown that CEMIP induces EMT." (PMID 31303964, 2019). "This investigation uncovered a novel CACS19-related ceRNA mechanism whereby CACS19 enhanced CEMIP by physically harboring miR-140-5p and abolishing its availability, thus contributing to CRC cell proliferation and tumor growth." (PMID 31744051, 2019). "Our finding that knocking out CEMIP markedly attenuates xenograft growth provides the first in vivo data demonstrating a critical role for CEMIP expression in colon cancer tumor growth, thus suggesting that CEMIP directly contributes to tumor phenotype and may itself be a therapeutic target." (PMID 26437221, 2015). "In this case, CEMIP positively regulates GRP78 levels, facilitating tumor growth and metastasis." (PMID 40278350, 2025).
tumor (continued). "CEMIP-expressing metastases showed evidence of vascular co-option, presumed to enable tumor cells to cross the blood–brain barrier, and the invasion of brain slices was enhanced by CEMIP EVs but not EVs from cells in which CEMIP expression was knocked out." (PMID 39851567, 2025). "Our findings in tumorigenic 293T cells indicate that CEMIP inhibition does not influence tumor cell proliferation under the cell culture conditions utilized in this study." (PMID 39454959, 2024). "Specifically, CEMIP is key in facilitating EMT, growth of tumor cells, invasion, and metastasis." (PMID 38761291, 2024). "Therefore, CEMIP may activate the Wnt/β-catenin signaling pathway to stimulate the polarization of macrophages into M2 macrophages and to secrete corresponding anti-inflammatory factors, which may promote the immune escape of tumor cells and increase the probability of metastasis." (PMID 37662915, 2023). "In vivo analyses revealed that exosomal CEMIP alters the morphogenesis of BMEC due to its ability to elicit a proinflammatory phenotype in brain vasculature and microglial cells, thereby fostering tumor cell metastasis and cerebral colonization." (PMID 37958619, 2023). "Additionally, CEMIP affects EMT signaling molecules including TGF-β, PI3K, and AKT in a mouse xenograft NSCLC tumor model." (PMID 35177031, 2022). "Because tumor material of the metastases developed under the targeted therapy was not available, we were not able to proof if the molecular chaperones and CEMIP were overexpressed in vivo and contributed in fact to the development of the metastases." (PMID 29371980, 2017). "Therefore, CEMIP may have a positive correlation with MMP2, MMP7, MMP13, and MMP14 and regulate tumor cell EMT through MMPs to promote tumor cell migration." (PMID 37662915, 2023). "Studies have shown that the anti-CEMIP monoclonal antibody (anti-CEMIP), ipriflavone, and paclitaxel (PTX) combined with the latest nanosphere-targeted drug delivery technology can make CEMIP as a therapeutic target to inhibit inflammation or tumor development." (PMID 37662915, 2023). "Therefore, it is not unlikely that CEMIP serves a protective function under the hypoxic conditions within the tumor environment." (PMID 31303964, 2019). "Moreover, the correlations of CEMIP with tumor immune infiltration in BC are still not determined." (PMID 34966410, 2021). "A marked increase in cleaved caspase-3 was detected in tumors from CEMIP negative DLD-1 cells, suggesting that knocking out CEMIP impedes tumor growth by inducing increased apoptosis." (PMID 26437221, 2015).
infection (6 papers, 2014 to 2024). The state of being infected such as from the introduction of a foreign agent such as serum, vaccine, antigenic substance or organism. "Studies employing CEMIP knockout mice elucidate its role in regulating inflammatory responses, wound healing, and infection." (PMID 38390387, 2024). "In the mice with knockout of the CEMIP gene, the proliferation and infection abilities of S. aureus were significantly reduced, and the skin wound recovered faster than that in normal mice." (PMID 37662915, 2023). "The infiltration of local neutrophils, DCs, and monocytes was increased in CEMIP−/− mice, which may help fight against infection." (PMID 37662915, 2023).
adenocarcinoma (3 papers, 2011 to 2015). A common cancer characterized by the presence of malignant glandular cells. "A Chi-square test with exact p-value suggests that adenocarcinomas have a significantly higher percentage of tissue samples presenting with CEMIP positive staining (p-value < 0.0001)." (PMID 26009875, 2015).
bacterial infections (1 paper, 2023). "At the same time, CEMIP also plays a complex and important role in promoting fibrosis and bacterial infection." (PMID 37662915, 2023). "However, it remains unclear how bacterial invasion induces CEMIP production, why only CEMIP was elevated, and whether this phenomenon occurs across different bacterial infections." (PMID 37662915, 2023).
genetic disorders (1 paper, 2024). "Of these, only deficiencies in HYAL1, HYAL2, HYAL3 and CEMIP have been identified as the cause or putative cause of human genetic disorders." (PMID 39056785, 2024).
CEMIP also shares sentences with these, for which no sentence is quoted: cervical carcinoma (7 papers); hepatocellular carcinoma (7); cholangiocarcinoma (4); colon adenoma (3); colorectal tumors (3); oral squamous cell carcinoma (3); ductal breast carcinoma (2); fibrosis (2); laryngeal carcinoma (2); laryngeal squamous cell carcinoma (2); lymphoma (2); melanoma (2); osteoporosis (2); pancreatic adenocarcinoma (2); renal cell carcinoma (2); acute pancreatitis (1); Ataxia (1); cataract (1); cervical intraepithelial neoplasia (1); cholestasis (1); colorectal adenocarcinoma (1); ductal carcinoma in situ (1); fibroma (1); heart failure (1); Hepatic hemangioma (1); Hepatic steatosis (1); inflammatory bowel disease (1); Insulin resistance (1); keratoconus (1); knee osteoarthritis (1).
A further 19 diseases each share a sentence with CEMIP in 1 paper.